MYC (MYC proto-oncogene, bHLH transcription factor)
Diseases named in the same sentence as MYC in open-access papers (continued):
Sharing a sentence is not in itself a finding about the gene and the disease.
B-cell lymphoma (571 papers, 2006 to 2026). "While the presence of a MYC rearrangement is the hallmark of BL, other aggressive B-cell lymphomas can also have MYC rearrangements." (PMID 41154426, 2025). "According to other genetic studies, BCLs with MYC rearrangement often contain genetic abnormalities linked to mature B-cell lymphomas, whereas B-ALL with MYC rearrangement often lacks additional mutations." (PMID 41142614, 2025). "In MCL, MYC translocations are less common compared to other B-cell lymphomas but have been associated with blastoid variant morphologies and poor outcomes." (PMID 40002289, 2025). "MYC mutations are detected in 30–50% of RT patients, and aberrant MYC activity is a major driver of the aggressive phenotype observed in B-cell lymphomas." (PMID 40565027, 2025). "Despite being a defining feature of LBCL‐IRF4‐R, IRF4 rearrangement is not exclusive to this subtype, as it can also occur in other aggressive B‐cell lymphomas, particularly those associated with MYC or BCL2 rearrangements." (PMID 39415926, 2024). "The recent discovery of the aberrant expression of DDX3Y compensating the loss of DDX3X function in tumors with c-MYC activation has opened a new area for developing new therapeutic strategies for B cell lymphomas." (PMID 37035206, 2023). "Major changes have been made in the diffuse large B-cell lymphomas (DLBCL)/high-grade B-cell lymphomas (HGBL) associated with MYC and BCL2 and/or BCL6 rearrangements." (PMID 37190213, 2023). "The individual loss of the genes encoding PUMA or BIM (even loss of one allele) substantially accelerates MYC-driven pre-B/B cell lymphoma in mice carrying an Eμ-MYC transgene." (PMID 36342579, 2023). "MYC overexpression, caused by gene rearrangements and mutations, has been observed in various hematological malignancies, especially in invasive B-cell lymphomas, such as DLBCLs and BLs." (PMID 36982568, 2023). "Mutations in these pathways are thus frequently found in c-MYC-driven B-cell lymphomas, as reviewed in." (PMID 37035206, 2023). "Since it has been found that IRF4 rearrangement can occur in some other aggressive B‐cell lymphomas as well, especially those which are associated with MYC or BCL2 rearrangement, mainly in adults." (PMID 37081786, 2023). "All patients with a CWE and non-Hodgkin B cell lymphoma with bone localization exhibited a c-MYC mutation." (PMID 37796407, 2023). "High-grade B-cell lymphoma with translocations of MYC and BCL2 and/or BCL6 genes has been associated with a worse prognosis, whereas mutations such as MYD88 and CD79B have been frequently described in PCNSL." (PMID 37240953, 2023). "For a diverse range of B-cell lymphomas, a reduced level of MYC expression has been associated with patient survival." (PMID 35563017, 2022). "We show that MYC activity is closely correlated with OxPhos‐associated gene signatures in human B‐cell lymphomas and sensitizes B cells to the mitochondrial complex I inhibitor IACS‐010759." (PMID 34632715, 2022). "Particularly, it is required for the definition of the high-grade B-cell lymphoma with MYC associated to BCL2 and/orBCL6 rearrangements." (PMID 33768318, 2021). "Its loss profoundly delayed MYC-mediated B-cell lymphoma development due to increased B-cell apoptosis mediated by MYC." (PMID 32549409, 2020). "MYC is commonly dysregulated in aggressive B-cell lymphomas by gene rearrangements, amplifications or mutations." (PMID 32260556, 2020).
B-cell lymphoma (continued). "This heterogeneity likely underscores the complexity of the genomic mechanisms underlying MYC aberrations in B cell lymphoma." (PMID 31932576, 2020). "On the contrary, overexpression of BCL-XL and MYC caused B-cell lymphoma, and overexpressed MCL-1 accelerated MYC-driven B-cell lymphoma development." (PMID 32575557, 2020). "Although MYC was suggested to drive MDM2 expression based on its association with the MDM2 promoter in B cell lymphoma cells, to our knowledge, this is the first demonstration that MYC overexpression upregulates MDM2 protein." (PMID 33425720, 2020). "The BCL2 gene is involved in apoptosis and its co-expression with the oncogene MYC is associated with a poor prognosis in B-cell lymphoma patients." (PMID 30866419, 2019). "Another study investigating the P493-6 B-cell line carrying an inducible MYC allele and primary MYC-associated B-cell lymphoma samples, showed that lncRNAs are the principal element of the MYC-regulated transcriptional program." (PMID 28947998, 2017). "One of the most influential transcription factors, commonly associated with unfavorable prognosis for patients with B cell lymphoma, is nuclear phosphoprotein MYC." (PMID 28375188, 2017). "In Eμ-MYC transgenic mice, where MYC overexpression drives B-cell lymphoma, NFκB2 loss accelerates tumor development by impairing MYC-dependent apoptosis, highlighting the tumor suppressor function of the non-canonical NFκB pathway." (PMID 26556860, 2015). "In aggressive B-cell lymphomas, c-MYC-mediated recruitment of EZH2 causes H3K27me3-dependent silencing of the tumor suppressor miR-26a, and c-MYC or EZH2 inhibitors reactivate miR-26a expression in this malignancy." (PMID 25968566, 2015). "While Pim-1 and MYC transgenic mice were predisposed to T- and B cell lymphomas, respectively, double transgenic Eμ Pim-1 and Eμ MYC developed an aggressive pre-B leukemia in utero with death at or before birth." (PMID 26186558, 2015). "Given that human MYC is mutated in an AID-dependent fashion in some human B cell lymphomas and undergoes recurrent chromosomal translocations with IGH, it, like mouse c-Myc, is likely a target of AID in GC B cells." (PMID 22768095, 2012). "In our study, unfavorable targets in plasma were associated with poor prognosis in B-cell lymphomas, mainly MYC mRNA." (PMID 20016842, 2009). "Notably, elevated ARMC12 and MYC levels were also linked to poor outcome of adrenocortical sarcinoma, B-cell lymphoma, renal clear cell carcinoma, or breast tumor." (PMID 41510169, 2026). "Conversely, differential diagnosis should consider a rare B-ALL/LBL variant with MYC rearrangement, displaying characteristics of mature B-cell lymphomas (BCLs), such as CD20 positivity, TdT negativity, smIg expression, light chain restriction, and the IGH-BCL2 translocation." (PMID 41142614, 2025). "Notably, BTK, AKT, and PI3K are well-established targets implicated in B-cell lymphoma and leukemia, while MYC is also a key oncogene associated with these diseases." (PMID 40235547, 2025). "Consistent with the complex genomic landscape and prevalence of genetic aberrations identified in EBL, the transcriptional analysis detected an enrichment of high-grade signatures, including c-MYC-related signaling, which is observed in aggressive variants of large B-cell lymphomas." (PMID 41008822, 2025). "Taken together, the results of this study indicate that the caspase cleavage of ROCK1 influences the characteristics of c-MYC-induced B cell lymphomas, which were associated with greater numbers of bone marrow macrophages, altered bone marrow cell cycle profiles and decreased cellularity." (PMID 38616733, 2024). "And indeed, loss of Nfkb2 gene accelerated B cell lymphoma (BCL) development in Eμ-MYC tg mice, whereas the Nfkb1 gene was shown to be dispensable for MYC-induced lymphomagenesis, and overall NF-κB and Calcineurin (CN)–dependent NFATc2 activation induced apoptosis in human BL cells." (PMID 37546418, 2023).
B-cell lymphoma (continued). "In our cohort, all patients with CWE and non-Hodgkin B cell lymphoma with bone localization had a c-MYC mutation which may support this hypothesis." (PMID 37796407, 2023). "This implies that the CB-839 mTOR inhibitor combination may be susceptible to patients with therapeutic MYC-translocated B-cell lymphomas." (PMID 35204484, 2022). "Indeed, we have recently found that a hydroxylated variant of ternatin-4 is efficacious in a mouse model of MYC-dependent B cell lymphoma." (PMID 36264623, 2022). "Furthermore, PIAS1-induced MYC sumoylation stabilizes MYC and facilitates MYC phosphorylation-associated transactivation in B-cell lymphomas." (PMID 35887358, 2022). "Tumor suppressormiR-146a knockout mice spontaneously develop B cell lymphomas and myeloid malignancies. miR-146b and miR-146a knockout mice develop histologically distinct B cell lymphomas. miR-146a deficiency accelerates c-MYC-induced B cell lymphoma development." (PMID 33953721, 2021). "The aberrant activation of the SUMOylation pathway is a hallmark of MYC-driven B-cell lymphomas." (PMID 34503213, 2021). "Furthermore, PIAS1-induced SUMOylation stabilizes MYC, and PIAS1 is implicated in facilitating transactivation-associated phosphorylation of MYC in B-cell lymphomas." (PMID 34503213, 2021). "However, alterations involving the MYC oncogene, such as translocations or overexpression of MYC, are a hallmark of B cell lymphoma pathogenesis." (PMID 31454887, 2019). "Burkitt lymphoma (BL) is a highly aggressive B-cell lymphoma associated with MYC translocation." (PMID 30104685, 2018). "This suggests that patients with treatment-resistant MYC-translocated NH B-cell lymphomas might be susceptible to a combination of CB-839 and mTOR inhibitor." (PMID 30564554, 2018). "Conversely, ARTD8-deficient mice showed a reduced susceptibility to c-MYC-induced B-cell lymphoma." (PMID 26654227, 2015). "It is worth noting that MYC is significantly mutated by AID in certain human B cell lymphomas." (PMID 22768095, 2012). "Moreover, loss of PUMA enhances c-MYC-driven B-cell lymphoma development in mice." (PMID 28424416, 2017). "Aggressive B-cell lymphomas, driven by MYC overexpression, exhibit rapid progression, resistance to therapies, and poor survival." (PMID 41680300, 2026). "Our case involved high-grade B-cell lymphoma with MYC and BCL2 rearrangement (double hit), treated with dose-adjusted etoposide, prednisone, vincristine, cyclophosphamide, and doxorubicin chemotherapy, resulting in complete resolution." (PMID 41884745, 2026). "Overall, our results uncover targetable vulnerabilities in MYC-driven B cell lymphomas, possibly extending to other aggressive B cell tumors silencing BCR expression." (PMID 41668618, 2026). "Burkitt lymphoma is a highly aggressive mature B-cell non-Hodgkin lymphoma characterized by MYC dysregulation and a high proliferative index." (PMID 42051830, 2026). "The integration of these genomic findings supports the classification as DLBCL/high-grade B-cell lymphoma with MYC and BCL2 rearrangements." (PMID 41374977, 2025). "The transcription factor c-MYC (MYC) was the first oncogene deregulated by chromosomal translocation to be identified in B-cell lymphoma." (PMID 40721291, 2025). "MYC translocations have been identified in many aggressive B-cell lymphomas (e.g., Burkitt lymphomas and double-hit lymphomas)." (PMID 40002289, 2025).
B-cell lymphoma (continued). "Concurrent rearrangements of MYC and BCL2 are hallmark alterations in aggressive B-cell lymphomas, also known as double-hit lymphomas, which are classified as high-grade B-cell lymphomas (HGBCLs)." (PMID 41301875, 2025). "GPM confirmed the presence of both IGH::BCL2 and PAX5::MYC, along with 11q aberrations and other complex genomic abnormalities, supporting a diagnosis of DLBCL/high-grade B-cell lymphoma with MYC and BCL2 rearrangements." (PMID 41374977, 2025). "High-grade B-cell lymphomas with MYC and BCL2 and/or BCL6 rearrangements represent aggressive entities." (PMID 41364305, 2025). "These overlapping immunophenotypes between mature B-cell neoplasms and lymphoblastic leukemia were also documented in previous reports of 89 patients with various MYC-rearranged mature B-cell lymphoma subtypes." (PMID 41142614, 2025). "With FISH analysis, we identified three cases of DLBCL/high-grade B-cell lymphoma (HGBCL) with MYC and BCL2 rearrangements." (PMID 40507898, 2025). "About 2% of cases of diffuse large B-cell lymphoma (DLBCL) or high-grade B-cell lymphoma (HGBCL) with MYC and BCL2 rearrangements show expression of terminal deoxynucleotidyl transferase (TdT)." (PMID 41142614, 2025). "Image-guided core biopsy established the diagnosis of high-grade B-cell lymphoma with MYC rearrangement, and the patient achieved complete radiologic remission following systemic chemoimmunotherapy." (PMID 41362384, 2025). "In general, B-cell lymphomas driven by MYC dysregulation are characterized by genomic instability and metabolic reprogramming to support rapid cell proliferation." (PMID 41008653, 2025). "High-grade B-cell lymphoma with MYC and BCL2 and/or BCL6 rearrangements constitutes a distinct clinicopathological entity characterized by aggressive behavior, inherent resistance to conventional immunochemotherapy, and suboptimal clinical outcomes." (PMID 41364305, 2025). "The majority of cases are diffuse large B-cell lymphomas (DLBCLs); however, within this classification, high-grade B-cell lymphomas (HGBLs) are distinguished based on specific genetic alterations (MYC, BCL2, and BCL6 translocations) and histological features." (PMID 40243506, 2025). "DHITsig was originally identified in high-grade B cell lymphoma with MYC and BCL2 rearrangements (HGBCL-DH-BCL2)." (PMID 40674145, 2025). "High‐grade B‐cell lymphoma with MYC and BCL2 and/or BCL6 rearrangements (clinically often referred to as double hit lymphoma [DHIT] or triple hit lymphoma) and HGBL, NOS, were newly introduced in the 4th revised WHO classification." (PMID 39545339, 2025). "The pathological subtypes of R/R B-NHL in this cohort were DLBCL, primary mediastinal lymphoma (PML), primary central nervous system lymphoma (PCNSL) and high-grade B-cell lymphoma (HGBL) with MYC and/or BCL2/BCL6 rearrangement." (PMID 40078989, 2025). "FISH analysis of a large B-cell lymphoma revealed an atypical MYC rearrangement with amplification (ampR1-3G), an atypical BCL6 rearrangement (1-3R2-3F signal pattern), and no IGH::MYC fusion." (PMID 41010038, 2025). "Burkitt lymphoma is a highly aggressive B-cell non-Hodgkin lymphoma closely associated with Epstein-Barr virus (EBV) infection and driven by MYC oncogene overexpression." (PMID 41180747, 2025). "We recognize several chromosomal rearrangements in the genome of the large B-cell lymphomas, among the most frequent are genes MYC and BCL2 and/or BCL6." (PMID 40126346, 2025). "EZB subtype was primarily confined to GCB-DLBCL NOS (16%) and specific germinal center-derived DLBCL subtypes, such as T-cell Histiocyte-Rich B-cell Lymphoma and DLBCL/High-Grade B-cell Lymphoma with MYC and BCL2 dual hits." (PMID 40067847, 2025).
B-cell lymphoma (continued). "Meanwhile, HGBL with two or three rearrangements, due to its high molecular and histological heterogeneity, has been redefined as “diffuse large B-cell lymphoma/high-grade B-cell lymphoma with MYC and BCL2 rearrangements”." (PMID 40243506, 2025). "Burkitt Lymphoma (BL), an aggressive B-cell lymphoma driven by MYC translocations, requires intensive chemotherapy treatments which deliver high effectiveness yet increase future risks of developing secondary malignancies." (PMID 40772229, 2025). "In five patients, the initial diagnosis of high-grade B-cell lymphoma was later revised to BL owing to the delayed identification of MYC rearrangement or aberrant MYC expression, complicating timely diagnosis." (PMID 40703543, 2025). "Burkitt lymphoma is an aggressive subtype of non-Hodgkin B-cell lymphoma, characterized by the rapid proliferation of B-cells due to a translocation involving the MYC gene on chromosome 8." (PMID 41180747, 2025). "Diffuse large B-cell lymphoma/high-grade B-cell lymphoma with MYC and BCL2 rearrangements (DLBCL/HGBL-MYC/BCL2) represents a distinct entity of mature aggressive B-cell lymphoma, which is either de novo DLBCL or transformed from indolent lymphoma." (PMID 40230856, 2025). "Diffuse large B-cell lymphoma/high-grade B-cell lymphoma with MYC and BCL2 rearrangements (DLBCL/HGBL-MYC/BCL2) represents a distinct entity of mature aggressive B-cell lymphoma, constituting a substantial gap in the clinical management of DLBCL." (PMID 40230856, 2025). "MYC regulation by the CBM signalosome was first noted in B-cell lymphoma, where CARD11 can drive MYC activity to promote cellular proliferation." (PMID 41346415, 2025). "Most patients were diagnosed with DLBCL (37 patients, 97%), whereas one patient had high-grade B-cell lymphoma with MYC and BCL2 rearrangements." (PMID 39907880, 2025). "The exact frequency of IGK::MYC or IGL::MYC fusions in high-grade B-cell lymphomas, including Burkitt lymphoma, remains uncertain due to limited clinical testing for IG light chains." (PMID 41374977, 2025). "Double-hit lymphoma (DHL), a subtype of high-grade B-cell lymphoma characterized by rearrangements of MYC and BCL2 and/or BCL6 genes, represents an aggressive form of large B-cell lymphoma." (PMID 40961031, 2025). "This category was maintained by the most recent classifications including exclusively high-grade B-cell lymphoma (HGBL) with MYC and BCL2 rearrangements (MYC/BCL2)." (PMID 41008653, 2025). "In contrast, studies in MYC-driven B-cell lymphoma models demonstrated the opposite effect: ROS-lowering doses of antioxidants such as NAC and vitamin C reduced tumor growth, induced apoptosis, and increased survival." (PMID 40646353, 2025). "Burkitt lymphoma (BL), a rare, aggressive MYC-driven B-cell non-Hodgkin lymphoma (NHL), has endemic, sporadic, and immunodeficiency-associated variants." (PMID 40703543, 2025). "All these cases were classified as high-grade B-cell lymphoma/DLBCL DH (MYC and BCL2) based on histopathological evaluation." (PMID 40067847, 2025). "This regimen has also been investigated in patients with MYC-rearranged aggressive B-cell lymphoma and demonstrated high efficacy in a multi-center phase II trial." (PMID 41154426, 2025). "PAX5::MYC fusion has been reported in high-grade B-cell lymphoma with MYC and BCL2 rearrangements, DLBCL, and transformed FL." (PMID 41374977, 2025). "Knockout of Usp29 significantly prolongs the survival of tumor-bearing mice by reducing the expressions of MYC and HIF1α in neuroblastoma and B-cell lymphoma." (PMID 39664521, 2024). "Previously, our research has demonstrated that IBTK haploinsufficiency also influences the tumor microenvironment in a mouse model of MYC-driven B-cell lymphoma." (PMID 38371626, 2024). "Designating these cases as DHL/THL and qualifying with TdT expression (e.g., “High grade B-cell lymphoma with MYC and BCL2 rearrangements, and expression of TdT”) is preferred by the panel." (PMID 37530792, 2024).